TMCC3 (transmembrane and coiled-coil domain family 3)
Synonyms: KIAA1145
Tractability: Antibody: UniProt predicts a signal peptide or a membrane-spanning region. PROTAC: its protein half-life has been measured.
Gene: Protein-coding gene on chromosome 12 (94,567,122 to 94,650,557, reverse strand). Ensembl gene ENSG00000057704.
Subcellular location: Endoplasmic reticulum membrane
Subcellular location (Human Protein Atlas): Endoplasmic reticulum; Vesicles
Gene Ontology:
Molecular function: 14-3-3 protein binding; identical protein binding; protein binding
Cellular component: endoplasmic reticulum; endoplasmic reticulum membrane; endomembrane system
Genetic constraint (gnomAD): Loss-of-function variants: 21 observed, 29.14 expected, observed/expected ratio (o/e) 0.72, 90% interval 0.51 to 1.04. The upper end of that interval is the gene's LOEUF score, 1.04, which puts it in group 4 of 6, group 1 being the genes least tolerant of losing a copy. Missense variants: 400 observed, 437.67 expected, observed/expected ratio (o/e) 0.91, 90% interval 0.84 to 0.99. Synonymous variants: 177 observed, 174.09 expected, observed/expected ratio (o/e) 1.02, 90% interval 0.9 to 1.15.
Homologues: Orthologues: chimpanzee TMCC3 (99% identical), macaque TMCC3 (95% identical), dog TMCC3 (95% identical), mouse Tmcc3 (94% identical), rat Tmcc3 (92% identical), guinea pig TMCC3 (89% identical), rabbit TMCC3 (89% identical), pig TMCC3 (80% identical), tropical clawed frog tmcc3 (80% identical), zebrafish tmcc3 (57% identical), Drosophila melanogaster Dmtn (36% identical), Caenorhabditis elegans C15H9.4 (21% identical). Paralogues in human: TMCC2 (55% identical), TMCC1 (51% identical), TEX28 (23% identical).
Diseases named in the same sentence as TMCC3 in open-access papers:
TMCC3 is named in the same sentence as 18 diseases in open-access papers, as found by Europe PMC text mining. Sharing a sentence is not in itself a finding about the gene and the disease. The quoted sentences say what the papers report.
breast carcinoma (2 papers, 2021 to 2025). "More importantly, we found that high TMCC3 expression adversely impacted clinical outcome in early-stage luminal breast cancer." (PMID 33742122, 2021). "Using these two short-term cultured cells and established breast cancer cell lines, we compared the expression levels of TMCC3 in mammosphere-cultured (Sphere) and monolayer-cultured (2D) cells." (PMID 33742122, 2021). "Clinically, high TMCC3 expression is an independent poor prognostic factor in breast cancer, including early-stage breast cancer." (PMID 33742122, 2021). "To delineate the involvement of TMCC3 in metastasis of breast cancer, we examined the expression of TMCC3 in metastatic lesions of breast cancer PDXs." (PMID 33742122, 2021). "Clinically, TMCC3 mRNA expression in 202 breast cancer specimens as determined by qRT-PCR assay showed that higher TMCC3 expression correlated with poorer clinical outcome of breast cancer, including early-stage breast cancer." (PMID 33742122, 2021). "The expression level of TMCC3, if confirmed to be highly prognostic in future study, will make TMCC3 as a simple and valuable biomarker for early-stage luminal breast cancer." (PMID 33742122, 2021). "To evaluate the clinical relevance of TMCC3 expression, we examined the mRNA levels of TMCC3 in tumor specimens of 202 patients with breast cancer by qRT-PCR." (PMID 33742122, 2021). "Our study is the first to demonstrate the prognostic significance of TMCC3 in breast cancer." (PMID 33742122, 2021). "We demonstrated greater expression of TMCC3 in BCSCs than non-BCSCs and higher expression of TMCC3 in metastatic lymph nodes and lungs than in primary tumor of breast cancer PDXs." (PMID 33742122, 2021). "To confirm the differential expression levels of TMCC3 protein in BCSCs enriched populations and non-BCSCs, we determined BCSC enrichment markers in three breast cancer PDXs." (PMID 33742122, 2021).
autism (1 paper, 2022). Persistent deficits in social interaction and communication and interaction as well as a markedly restricted repertoire of activity and interest as well as repetitive patterns of behavior. "The fivefold downregulated MPO, TMCC3, MMP8, CA1, and ELF3 genes and the fivefold upregulated MTRNR2L8 gene can be considered for the early identification of autism patients among Saudis." (PMID 35215271, 2022).
cervical cancer (1 paper, 2021). A primary or metastatic malignant neoplasm involving the cervix. "Using an online DNA microarray database at the ONCOMINE website, we found higher mRNA level of TMCC3 in cancer part than normal tissue in cervical cancer, prostate cancer, pancreatic cancer, lung cancer, glioblastoma, skin cancer, hepatoma, and thyroid gland papillary carcinoma." (PMID 33742122, 2021).
chronic lymphocytic leukemia (1 paper, 2021). "Through analysis of proteomics profiling of colorectal cancer and chronic lymphocytic leukemia, TMCC3 protein level was found to be greater in cancer parts than their normal counterparts." (PMID 33742122, 2021).
epilepsy (1 paper, 2023). A brain disorder characterized by episodes of abnormally increased neuronal discharge resulting in transient episodes of sensory or motor neurological dysfunction, or psychic dysfunction. "In consideration of species conservation, we jointly analyzed the sequencing results of human peripheral blood samples and mouse tissue samples, and four genes (GADD45B, TMCC3, TPGS2, and KCNJ2) were identified as hub genes in IS and epilepsy." (PMID 37792772, 2023). "However, the involvement of TMCC3 and TPGS2 in IS and epilepsy has not been elucidated." (PMID 37792772, 2023).
gastric cancer (1 paper, 2021). A primary or metastatic malignant neoplasm involving the stomach. "Using Kaplan–Meier Plotter website to evaluate the clinical significance of TMCC3 in cancer progression, we showed that higher expression of TMCC3 correlated with poor OS of patients with ovarian, lung, and gastric cancer." (PMID 33742122, 2021).
rectal cancer (1 paper, 2025). A primary or metastatic malignant neoplasm that affects the rectum. "This study identified a TRP channel-related gene signature (BMP5, DHRS11, GLTP, NFE2L3, and TMCC3) that predicts rectal cancer prognosis and modulates tumor–immune crosstalk." (PMID 40963625, 2025).
cancer (2 papers, 2021 to 2025). A tumor composed of atypical neoplastic, often pleomorphic cells that invade other tissues. "Concurrently, TMCC3 is known to sustain cancer stem cell properties by activating the AKT pathway." (PMID 40963625, 2025).
tumor (2 papers, 2021 to 2025). "Notably, the expression level of tumor TMCC3 was an independent risk factor for RFS (HR: 2.81, 95% CI: 1.45–5.45, p = 0.002) and OS (HR: 2.28, 95% CI: 1.31–3.96, p = 0.004)." (PMID 33742122, 2021). "The conserved tumor-promoting role of TMCC3 across malignancies suggests broad therapeutic targeting potential." (PMID 40963625, 2025). "The results indicated that RFS correlated with patients aged ≥50 years (HR: 2.74, 95% CI: 1.43–5.24, p = 0.002) and Grade III (HR: 1.89, 95% CI: 1.04–3.46, p = 0.038), and higher expression of TMCC3 in tumor (HR: 3.32, 95% CI: 1.89–5.83, p = 0.001)." (PMID 33742122, 2021). "The relative fold of CD44+TMCC3+ subsets in metastatic lymph node was 2.72 ± 0.7, as compared with primary tumor cells (n = 5, p = 0.04)." (PMID 33742122, 2021). "In conclusion, we provide the first evidence supporting that TMCC3 plays important roles in maintaining BCSCs features, tumor metastasis, and tumorigenicity." (PMID 33742122, 2021). "Early-stage patients with low expression of TMCC3 in tumor part had significantly greater RFS (p < 0.001) and OS (p < 0.001) than patients with high expression levels." (PMID 33742122, 2021). "We also examined the tumor growth of TMCC3 overexpressing MCF7 in vivo." (PMID 33742122, 2021). "To examine the role of TMCC3 in tumor metastasis, we next determined whether TMCC3 silencing suppresses the migration of TMCC3 expressing BCSCs in migration assay." (PMID 33742122, 2021). "In addition, OS correlated with the patients aged ≥50 years (HR: 2.66, 95% CI: 1.42–4.96, p = 0.002), Grade III (HR: 1.89, 95% CI: 1.06–3.40, p = 0.032), stages III + IV (HR: 2.81, 95% CI: 1.62–4.89, p = 0.001) and higher expression of TMCC3 in tumor (HR: 2.92, 95% CI: 1.69–5.02, p = 0.001)." (PMID 33742122, 2021). "The lymph nodes and primary tumor of BC0145 PDX were harvested for staining with anti-CD44 and anti-TMCC3 antibodies." (PMID 33742122, 2021). "Based on these research findings, we speculate that the high expression of TMCC3 may indirectly induce the upregulation of PD-1 by stimulating the high expression of CD8+ T cells, thereby promoting tumor progression." (PMID 40963625, 2025).
TMCC3 also shares sentences with these, for which no sentence is quoted: colorectal cancer (1 paper); glioblastoma (1); hepatoma (1); infection (1); lung carcinoma (1); pancreatic cancer (1); prostate carcinoma (1); skin cancer (1); thyroid gland papillary carcinoma (1).